CTNND2 (catenin delta 2)
Diseases named in the same sentence as CTNND2 in open-access papers (continued):
Sharing a sentence is not in itself a finding about the gene and the disease.
lung adenocarcinoma (2 papers, 2022 to 2024). A carcinoma that arises from the lung and is characterized by the presence of malignant glandular epithelial cells. "CTNND2 (δ-catenin) was suggested as a potential cancer biomarker and was associated with the expression of markers of cancer stem cells in lung adenocarcinoma." (PMID 36712866, 2022).
medulloblastoma (2 papers, 2022 to 2025). A malignant, invasive embryonal neoplasm arising from the cerebellum. "Our finding is echoed by an observation using medulloblastoma cell lines, where silencing of CTNND2 reduced E-cadherin protein, although data on N-cadherin were not available." (PMID 39995975, 2025).
Obesity (2 papers, 2024 to 2025). Accumulation of substantial excess body fat. "Of them, Ctnnd2, Dap, Marchf6, Cmbl, Sdc2, Cpq, Stk3, Vps13b, Cox6c, Grhl2, Fzd6, Cthrc1, Lrp12, and Zfpm2 showed associations or had functions related to atherosclerosis or obesity." (PMID 40362477, 2025). "Despite several genome-wide studies implicating polymorphisms within CTNND2, a definitive role of CTNND2 in the pathogenesis of obesity has not yet been determined." (PMID 39275286, 2024).
astrocytoma (1 paper, 2011). "In addition, CTNND2 overexpression promoted proliferation, invasion and Rac1 activity of U251 astrocytoma cells." (PMID 22151302, 2011).
Barrett esophagus (1 paper, 2022). Esophageal lesion lined with columnar metaplastic epithelium which is flat or villiform. "In support of this we analysed scRNA-Seq data, demonstrating that the CTNND2-module is aberrantly deregulated in the epithelial cells derived from Barrett’s Esophagus in each of 4 separate BE patients." (PMID 35164838, 2022). "Using single-cell RNA-Seq data we show that one of these modules, a proto-cadherin module centered around CTNND2, is inactivated in Barrett’s Esophagus, a precursor lesion to EAC." (PMID 35164838, 2022).
esophageal squamous cell carcinoma (1 paper, 2022). Esophageal squamous cell carcinoma (ESCC) is a type of esophageal carcinoma (EC) that can affect any part of the esophagus, but is usually located in the upper or middle third. "While a number of previous studies have already indicated the potential importance of CTNND2/WNT-signaling in EAC, a potentially more striking observation is that deletion of CTNND1 has been shown to lead to esophageal squamous cell carcinoma (ESCC) development." (PMID 35164838, 2022).
gastric cancer (1 paper, 2015). A primary or metastatic malignant neoplasm involving the stomach. "Thus, CTNND2 is also a promising target for therapy of gastric cancer." (PMID 25154973, 2015).
glioblastoma (1 paper, 2022). The most malignant astrocytic tumor (WHO grade IV). "Based on analysis of TCGA data, reduced CTNND2 expression was associated with poor prognosis of glioblastoma, especially for the mesenchymal type." (PMID 36303547, 2022). "For example, CTNND2 loss-of-function mutation was found to be common in glioblastoma." (PMID 36303547, 2022).
prostate tumors (1 paper, 2018). "We found that the CTNND2 gene was frequently re-arranged in clinically significant prostate tumors, while insignificant cases did not harbor structural variations at the CTNND2 gene locus." (PMID 29849951, 2018).
prostatic adenocarcinomas (1 paper, 2010). "Neuronal synaptic junction protein δ-catenin (CTNND2) is often overexpressed in prostatic adenocarcinomas but the mechanisms of its activation are unknown." (PMID 21106062, 2010).
pulmonary arterial hypertension (1 paper, 2024). Pulmonary arterial hypertension (PAH) is a group of diseases characterized by mean pulmonary artery pressure >20 mmHg and elevated pulmonary arterial resistance leading to right heart failure. "The same gene, CTNND2, has also been associated with pulmonary arterial hypertension in SSc." (PMID 39061958, 2024). "It is conceivable that variants in the CTNND2 gene may play a role in the dysregulation of endothelial progenitor cells observed in vasculopathic complications of SSc, such as pulmonary arterial hypertension and scleroderma renal crisis." (PMID 39061958, 2024).
retinal degeneration (1 paper, 2025). Degeneration of the retina. "Further investigation into the TMEM97—| CTNND2 → ADAM10 pathway may lead to precise and actionable therapeutic strategies to treat retinal degeneration." (PMID 39995975, 2025).
scleroderma (1 paper, 2023). Scleroderma is a rare autoimmune connective tissue disorder characterized by abnormal hardening of the skin and, sometimes, other organs. "A study indicates that enriched genes including MPO (myeloperoxidase), RXFP1, CXCL11, CTNND2, BMPR2, TLR3, CCR2, and CAV1 are altered expressed in scleroderma." (PMID 38137330, 2023).
thymoma (1 paper, 2023). A neoplasm arising from the epithelial cells of the thymus. "The mutation frequencies of CDC27 (67% vs. 29%), CTNND2 (33% vs. 4%), KRTAP6‐1 (33% vs. 4%), and RERE (33% vs. 4%) trended to be higher in type B3 thymoma than other subtypes of thymomas, while the mutation frequency of MUC5B (0% vs. 32%) trended to be lower in type B3 thymoma." (PMID 36916520, 2023).
type 2 diabetes (1 paper, 2019). "In this context, a polymorphism located at this gene (rs6873671) has been significantly associated with human type 2 diabetes in two independent genome-wide studies, suggesting that CTNND2 is involved in the regulation of glucose metabolism." (PMID 31208038, 2019).
ulcerative colitis (1 paper, 2022). An inflammatory bowel disease involving the mucosal surface of the large intestine and rectum. "The authors claim that CTNND2/DAP may be a possible shared susceptibility locus between human ulcerative colitis and canine AF; however, it seems that such a statement would require further confirmation." (PMID 36430390, 2022). "Neither of these genes have been identified as being associated with the occurrence of IBD in humans; however, the DAP gene, which is located in the same region of the genome as CTNND2, is indicated as associated with ulcerative colitis (though not CD)." (PMID 36430390, 2022).
cancer (19 papers, 2013 to 2025). A tumor composed of atypical neoplastic, often pleomorphic cells that invade other tissues. "We also found catenin (cadherin-associated protein) (CTNND2) upregulation, an adhesive junction associated protein implicated in bone, pain sensitisation, brain development and cancer formation." (PMID 28705915, 2017). "When we used the CGHcall package, we also identified two patients with extra copies of the CTNND2 gene, which encodes a protein that promotes the disruption of the adhesion protein E-cadherin, favoring cell migration and therefore cancer metastasis." (PMID 26185765, 2015). "In this review, we will focus on the signaling regulatory functions of CTNND2 and its encoded protein δ-catenin in neuro-related diseases and cancers, and discuss the limitations of previous investigative studies and the challenges of the future researches on CTNND2 and δ-catenin signaling." (PMID 40213389, 2025). "Interestingly, differentially methylated CpG sites were also found within catenin delta 2 (CTNND2), which encodes for δ-catenin and is involved in brain and eye development but also overexpressed in cancers." (PMID 32933073, 2020). "In the case of FAM135B, FEV, CBFB, and CTNND2, the regulatory status inferred here is at odds with their documented cancer role, thereby indicating potential anomalous regulation whose resolution would be tractable to experimental investigation." (PMID 39484215, 2024). "On the other hand, “hub genes” of four other modules contain POU2F3 (↑), CENPH (↑), PCSK6 (↑) and HERC2 (↑), BCAR3 (↑), DOHH (↑), NLK (↑), SCN2A (↑), CACNA2D3 (↓) and CTNND2 (↓), which were commonly reported related to cancer." (PMID 27602771, 2016). "CTNND2 is overexpressed in human cancer, and exogenous CTNND2 overexpression promotes a malignant phenotype 45." (PMID 25154973, 2015). "Thus it is possible that the CDH18 gene and other nearby genes identified in cohort (including CTNND2, CDH12 and MYO10) play a mechanistic role in the observed connection between MetS and cancer risk." (PMID 23628382, 2013). "Furthermore, an increasing number of studies have demonstrated that CTNND2 is involved in various cancers and may serve as a novel biomarker for the diagnosis and treatment for these diseases." (PMID 40213389, 2025). "At the pan-cancer level, most signaling pathways, particularly PKP4, PKP2, JUP, and CTNND2, showed high levels of activation in the Hormone AR signaling pathway, but consistent inhibition of apoptosis, cell cycle, and DNA damage responses." (PMID 37924160, 2023). "In total, recurrent (>3) MEI were observed in 329 protein-coding genes of which 28 genes are annotated in the Cancer Gene Consensus with either oncogenic (ALK1, ERBB4, TSHR, PREX2, CTNNA2, CTNND2) or tumour suppression roles (EBF1, LRP1B, PTPRD, GPC5, ROBO2, PTPRT)." (PMID 35301290, 2022). "However, the rest of the genes (LGI1, PCSK2, CTNND2, SLC6A19, DAO, TMEM82 and CPNE7) could be related to CRC and have been previously identified in other types of cancer." (PMID 30940089, 2019).
tumor (10 papers, 2013 to 2026). "During the evolution of tumor cells, driver mutation occurred in a large number of oncogenic genes, including Smarca4, Cxcr4, Ctnnd2 and Ank1." (PMID 36424557, 2022).
neurodevelopmental disorder (5 papers, 2019 to 2025). A behavioral and cognitive disorder with onset during the developmental period that involves impaired or aberrant development of intellectual, motor, or social functions. "This study presents the largest clinical cohort of individuals with CTNND2 variants reported to date, providing a comprehensive view of the associated neurodevelopmental disorder." (PMID 41502569, 2025). "In this comprehensive study on CTNND2-related neurodevelopmental disorders, we combined detailed clinical phenotyping with functional studies in patient-derived iPSC models." (PMID 41502569, 2025). "Our findings place CTNND2 alongside other WNT-regulating genes such as APC, CHD8, and CTNNB1, whose disruption similarly causes variable neurodevelopmental disorders." (PMID 41502569, 2025). "Both the clinical presentation of the 53 individuals reported here with CTNND2-related neurodevelopmental disorders and the in vitro model of three patient-derived and three CRISPR-Cas9 generated neural cell lines show a high degree of variability." (PMID 41502569, 2025). "Our study supports a role for CTNND2 haploinsufficiency in the etiology of neurodevelopmental disorders due to abnormal GABA neuronal differentiation in the forebrain." (PMID 37465584, 2023).
neurological disorders (3 papers, 2015 to 2023). "Though not many cases have been observed, CTNND2 is somewhat similar to SHANK3 as alterations in both genes are associated with multiple neurological disorders." (PMID 33115499, 2020).
metabolic disease (1 paper, 2019). A congenital disorder (due to inherited enzyme abnormality) or acquired (due to failure of a metabolically important organ) disorder resulting from an abnormal metabolic process. "However, little is known about the implication of CTNND2 in metabolic diseases." (PMID 31208038, 2019).
CTNND2 also shares sentences with these, for which no sentence is quoted: attention deficit-hyperactivity disorder (2 papers); bipolar disorder (2); colorectal cancer (2); psychiatric disorder (2); atherosclerosis (1); cognitive decline (1); esophageal cancer (1); familial adult myoclonic epilepsy (1); glaucoma (1); glioma (1); infection (1); Insulin resistance (1); lymph node metastasis (1); megalencephalic leukoencephalopathy with subcortical cysts (1); Merkel cell carcinoma (1); myopathy (1); psoriasis (1); retinitis pigmentosa 23 (1).